TRIM22 (tripartite motif containing 22)
Diseases named in the same sentence as TRIM22 in open-access papers (continued):
Sharing a sentence is not in itself a finding about the gene and the disease.
cancer (26 papers, 2012 to 2025). A tumor composed of atypical neoplastic, often pleomorphic cells that invade other tissues. "A key finding was the involvement of TRIM22, a protein previously implicated in the regulation of cellular differentiation and proliferation in various cancers." (PMID 40075566, 2025). "TRIM22 has previously been implicated in cancer progression, and our results showed that Lyc.HCL can downregulate TRIM22 expression in a dose-dependent manner." (PMID 40075566, 2025). "TRIM22 has been implicated in promoting tumorigenesis and cancer progression, and previous reports suggested that Lyc.HCL modulates TRIM22 expression." (PMID 40075566, 2025). "Real-time PCR analysis showed that TRIM22 mRNA level was 2.42 fold higher in cancer tissues compared with that in adjacent normal tissues." (PMID 28977927, 2017). "The strongest overexpressed proteins in treated Caco-2 exosomes (eg, CD59, CRP, CTSD, HMMR, TRIM22) are involved as potential oncogenes in the pathogenesis of different cancers, including CRC." (PMID 25594007, 2014). "Hence, further extensive research is needed to investigate the functions of the TRIM family in various types of cancer, to identify other TRIM22 substrates and to dissect how these interactions affect the physiological function of the target protein." (PMID 40593126, 2025). "However, the precise functional role and expression of TRIM22 in human cancers remain somewhat ambiguous." (PMID 40075566, 2025). "These contradictory findings highlight the complex role of TRIM22 in different cancer types." (PMID 40075566, 2025). "By targeting TRIM22 and modulating the JAK2/STAT3 and ERK signaling pathways, Lyc.HCL may offer a promising strategy for the treatment of ESCC and other cancers in which TRIM22 plays a significant role." (PMID 40075566, 2025). "For TRIM22, studies show that it plays a contrasting role in different cancers." (PMID 40593126, 2025). "Secondly, while we demonstrated that Lyc.HCL inhibits cancer cell growth, metastasis, and invasiveness by targeting TRIM22 and modulating the JAK2/STAT3 and ERK pathways in vitro and in vivo, our in vivo experiments were limited to a subcutaneous xenograft model." (PMID 40075566, 2025). "Our study suggests that TRIM22 can be a promising target for the cancer treatment." (PMID 38199981, 2024). "Several TRIM22 isoforms play crucial roles in cancer biology." (PMID 38199981, 2024). "Targeting TRIM22 may present a promising therapeutic approach for the treatment of cancers, offering a new avenue for intervention in cancer therapy." (PMID 38199981, 2024). "The relationship of TRIM22 with the development of most human cancers has rarely been studied, and to date, the association between TRIM22 and the MAPK signaling pathway has not been reported." (PMID 37258577, 2023). "TRIM22 was one of ten TRIM genes upregulated in a cancer cell line." (PMID 33879231, 2021). "There have been some studies concerning TRIM22 in various human cancers." (PMID 33879231, 2021). "Our results extend the understanding of TRIM22 functions, especially in the field of cancer." (PMID 34489426, 2021). "TRIM22 protein was examined in 126 cases of NSCLC cancer specimens and 15 cases of normal lung tissue specimens using immunohistochemistry.In normal lung tissues, we observed weak/negative TRIM22 staining in normal bronchial epithelial cells and alveolar cells." (PMID 28977927, 2017). "Expression of TRIM22 in cancer tissues is 2.58 fold higher than that in normal tissues." (PMID 28977927, 2017). "There have been two studies concerning TRIM22 in human cancers." (PMID 28977927, 2017). "Since TRIM22 could regulate cancer cell proliferation, we checked the change of cell cycle progression." (PMID 28977927, 2017). "Thus, the function and status of TRIM22 in human cancer cells are somewhat vague and might be tissue-specific." (PMID 33879231, 2021).
cancer (continued). "We find that the genes specifically expressed in the supratentorial tumors from these publications (such as HLA-DRA, LYZ, CD74, F13A1, and TRIM22) tend to be expressed in cells within the microglia-type cluster, whereas the infratentorial tumors have higher expression of cancer cell-related genes." (PMID 31427603, 2019). "Expression pattern and biological roles of TRIM22 remains unknown in most human cancers." (PMID 28977927, 2017). "TRIM22, a member of the TRIM family, acts as an E3 ligase in the initiation and progression of various malignant tumors." (PMID 40593126, 2025). "Among TcoFs, the most inquisitive appears to be TRIM22, which regulates all currently validated AP-2δ and its correlation with TFAP2D changes depending on tissue context (cancer vs. normal)." (PMID 36552887, 2022). "Thus the function and status of TRIM22 in human cancer is quite vague and might be tissue specific." (PMID 28977927, 2017). "A recent report identified TRIM22 mRNA was upregulated in NCSLC cell lines using Q-PCR, suggesting its potential involvement in cancer development." (PMID 28977927, 2017). "Mechanistic studies targeting SP140’s immune pathways (e.g., PD-L1, TRIM22) and SP100’s DNA repair functions in underrepresented cancers (e.g., BLCA, OSCC) could refine therapeutic applications." (PMID 41188771, 2025). "The biological function and specific mechanism of TRIM22 in cancer have not been clearly described in the existing literature." (PMID 34489426, 2021). "Moreover, TRIM22 has recently been identified as a negative regulator of major histocompatibility complex class II (MHC-II) expression, indicating a direct immunosuppressive role of considerable interest in checkpoint blockade cancer immunotherapy." (PMID 40593126, 2025). "Collectively, our findings reveal that TRIM22 regulates cancer cell senescence by modulating the proteasomal degradation of PHLPP2 in HCC cells, suggesting that TRIM22 could potentially serve as a therapeutic target for treating cancer." (PMID 38199981, 2024).
bacterial infection (1 paper, 2023). "Interestingly, one of the two TRIMs that we found to restrict Mtb replication, TRIM22, was previously reported to participate to the host response to viral and bacterial infection, including Mtb, thus corroborating the reliability of the screening results." (PMID 37543647, 2023).
connective tissue disorder (1 paper, 2022). A disease involving the connective tissue. "Therefore, the role of TRIM22 in connective tissue disorders needs further elucidation and interpretation." (PMID 35609018, 2022).
TRIM22 also shares sentences with these, for which no sentence is quoted: leukemia (3 papers); rubella (3); brain arteriovenous malformation (1); congenital heart disease (1); corneal dystrophy (1); epilepsy (1); esophageal cancer (1); Flavivirus Infections (1); ganglioglioma (1); hyper-IgE syndrome (1); Immunodeficiency (1); liver disease (1); neurodegenerative disease (1); neurodevelopmental disorder (1); nevus (1); periodontitis (1); rectal cancer (1); respiratory diseases (1); Sjögren’s syndrome (1); skin tumor (1); thyroid carcinoma (1); viral diseases (1); Wiskott-Aldrich syndrome (1).